RUNX2 (RUNX family transcription factor 2)
Diseases named in the same sentence as RUNX2 in open-access papers (continued):
Sharing a sentence is not in itself a finding about the gene and the disease.
osteoporosis (continued). "Therefore, miR-205/Runx2 may be a target for the treatment of patients suffering from both T2DM and osteoporosis." (PMID 38732046, 2024). "Furthermore, NAT10 directly controls the expression of RUNX2 through ac4C modification, regulating osteoblast differentiation ability of BMSC in vitro; thus, it can be used as a new potential therapeutic target for osteoporosis." (PMID 38233839, 2024). "Suppression of miR-92b-3p expression increased NADPH oxidase 4 (Nox4) and NF-κB levels, decreased Smad7, BMP2, and Runx2 gene and protein expressions, and inhibited bone marrow mesenchymal stem cell (BMSC) proliferation and osteoblast differentiation, resulting in more severe osteoporosis." (PMID 37239124, 2023). "This may be the reason why Runx2 and other known osteoporosis-related genes were not identified as DEGs in our RNA-seq analysis." (PMID 36245484, 2022). "Elevated expression of SOX5 has been evident in bone marrow-derived MSCs of postmenopausal osteoporosis patients and its overexpression inhibits the osteogenic differentiation of MSCs supported by reductions in ALP activity and osteoblast marker levels (Collagen I and Runx2)." (PMID 35468879, 2022). "The traditional Chinese medicine mainly targeted to increase the expression of OPN, BMP-2 and Runx2 which finally resulted in reducing the broken trabecular bones in femur bones and increasing the activity of ALP combined with enhanced the content of total bone mineral density in osteoporosis rats." (PMID 36387862, 2022). "This study showed that WERC could protect against osteoporosis and suggested that the possible mechanism of WERC might be related to increased osteoblast differentiation by activating Runx2 signaling and inhibition of osteoclast differentiation by suppression of RANKL signaling." (PMID 29070038, 2017). "In light of the strong inhibition of Runx2 expression, however, BRD inhibitors might not be ideally suited for osteoporosis treatment, since the transcription factor Runx2 is needed for the onset of osteoblast differentiation from MSCs." (PMID 27598138, 2016). "In addition, glucocorticoid-induced osteoporosis in MC3T3-E1 cells was partially reversed by BN through inhibition of AKT, which, by upregulating FOXO1, enhanced expression of bone turnover markers (ALP, OCN, Runx2, and Col 1) and extracellular matrix mineralization." (PMID 34198266, 2021). "The BMP TGF-β signaling pathway can regulate the expression of the RUNX2 gene in BMMSCs through the classical Smad pathway and non-classical p38 pathway, thus regulating the differentiation and function of osteoblasts and playing an important role in the bone metabolism balance in osteoporosis." (PMID 33569383, 2020). "Moreover, although METTL3 targets Runx2, VEGF and different signaling pathways to promote osteogenic differentiation, it remains controversial whether METTL3 is a potential therapeutic target for osteoporosis, as METTL3 also activates osteoclasts and then increases bone resorption." (PMID 34993198, 2021). "For instance, in osteoporosis, the upregulated EZH2 and KDM5A and downregulated absent, small, or homeotic 1-like (ASH1L) genes suppress Wnt and Runx2 pathways by altering H3K4me3 and H3K27me3 levels." (PMID 32963550, 2020).
osteosarcoma (178 papers, 2010 to 2026). A usually aggressive malignant bone-forming mesenchymal neoplasm, predominantly affecting adolescents and young adults. "Amplification of the RUNX2 gene, often linked to chromosomal instability at 6p12-p21, appears to be an early event in osteosarcoma development and contributes to tumor progression." (PMID 40507962, 2025). "Consistent with this, its overexpression mirrors findings in osteosarcoma and metastatic carcinomas, where elevated RUNX2 levels are linked to increased aggressiveness and poorer survival rates." (PMID 41141138, 2025). "Among these, WWOX and RUNX2 have been repeatedly implicated in other bone-related cancers such as osteosarcoma, making them logical candidates for investigation in ES." (PMID 41141138, 2025). "Experimental data from osteoblast and osteosarcoma models have shown that loss or inactivation of WWOX leads to aberrant RUNX2 activity, contributing to oncogenic processes through deregulated osteogenic signaling." (PMID 41141138, 2025). "Initially identified for its role in osteogenesis, RUNX2’s oncogenic functions have been linked to osteosarcoma progression." (PMID 39075554, 2024). "The reduced expression of RUNX2 protein is associated with up-regulated miRNA in human Osteosarcoma cells." (PMID 37453970, 2023). "The datasets can be used by researchers to identify novel targets of RUNX2 and elucidate the role and underlying mechanism of RUNX2 in osteosarcoma pathogenesis and metabolic reprogramming." (PMID 37663774, 2023). "The datasets will be useful for researchers to uncover the role and underlying mechanism of RUNX2 in osteosarcoma." (PMID 37663774, 2023). "RUNX2 expression was linked to clinical progression indicators in patients with osteosarcoma in three more investigations published in the last year." (PMID 37370857, 2023). "It was also found that high WWOX expression was associated with reduced RUNX2 expression in osteosarcoma cell lines." (PMID 36271927, 2022). "RUNX1 has been associated with leukemia and solid tumor development in the skin, lung, intestine, and breast, while RUNX2 has been associated with osteosarcoma, thyroid carcinoma, as well as breast and prostate cancers." (PMID 36231060, 2022). "It has also been reported that ABL kinases protected tumor cells from apoptosis induced by TNF-related apoptosis-inducing ligand (TRAIL) and that a high expression level of RUNX2 is associated with poor prognosis in patients with osteosarcoma." (PMID 34136397, 2021). "Current studies report that AKT and its underlying signal FOXO1 negatively regulate Runx2 transcription in osteosarcoma and prostate cancer cells." (PMID 30486861, 2018). "Reduced Runx2 protein expression has been directly linked to upregulated miRNAs in human osteosarcoma cells compared with mesenchymal progenitor cells." (PMID 29042587, 2017). "In carcinogenesis, RUNX2 acts as a master regulator of disease progression, and was shown to be strongly implicated in the development of osteosarcoma." (PMID 24124450, 2013). "Deletion of WWOX (chromosome 16q23.1-q23.2) has been reported in 30% of osteosarcomas, but, perhaps more importantly, reduction of its expression occurs in up to 58% of specimens and is associated with elevated RUNX2 expression." (PMID 22685381, 2012).
osteosarcoma (continued). "Disruption of RUNX2 activity, especially through its overexpression, has been associated with impaired differentiation, increased proliferation, and other features characteristic of both in human and canine osteosarcoma." (PMID 40507962, 2025). "Moreover, combination therapy effectively downregulated the RUNX2/pAKT signaling pathway, which is implicated in osteosarcoma progression and drug resistance, thereby enhancing the pro-apoptotic effects of doxo while mitigating its limitations." (PMID 40332124, 2025). "Consequently, RUNX2 overexpression is regarded as a hallmark of osteosarcoma, with chemoresistant tumours displaying more aberrant RUNX2 expression than non-resistant tumours." (PMID 40806771, 2025). "By employing both 2D and 3D in vitro models using the aggressive SJSA-1 osteosarcoma cell line, we aim to elucidate the molecular mechanisms underlying this combination therapy, focusing on the protein kinase B (pAKT) and runt-related transcription factor 2 (RUNX2) signaling pathway." (PMID 40332124, 2025). "Among the three RUNX2-associated circRNAs analyzed, only the expression of circ_0076684 was found to be significantly correlated with crucial clinical parameters in osteosarcoma (OS) patients, including tumor size, lung metastasis, Enneking stage, and overall survival time." (PMID 38659042, 2024). "Furthermore, we examine RUNX2 oncogene that is associated with amplifications and it has been found to correlate to poor response to chemotherapy in osteosarcoma." (PMID 33757216, 2021). "Moreover, other authors further emphasize that while WWOX and RUNX2 are both critical in bone biology and osteosarcoma pathology, where RUNX2 overexpression is typically linked to higher tumor grade, metastasis, and poor prognosis, their roles have not been similarly delineated in ES." (PMID 41141138, 2025). "Thus, radiotherapy resistance in osteosarcoma may be caused by the combined action of RUNX2 and HIF-1α." (PMID 40806771, 2025). "A previous study also revealed that loss of RUNX2 could sensitize osteosarcoma to chemotherapy." (PMID 35851595, 2022). "RUNX2 establishes osteoblasts in a terminally differentiated state through cooperation with retinoblastoma tumor suppressor protein (pRb) and cyclin-dependent kinase inhibitor p27KIP1, and disruption of this cooperation is associated with dedifferentiation in high-grade osteosarcomas." (PMID 34831147, 2021). "RUNX2, a well-established osteosarcoma biomarker, promotes tumor progression by enhancing cell proliferation, invasion, and resistance to apoptosis." (PMID 40332124, 2025). "Emerging evidence suggests that aberrant RUNX2 expression is a key factor in osteosarcoma oncogenesis." (PMID 40806771, 2025). "Collectively, these findings positioned RUNX2 as a contributor to osteosarcoma pathogenesis and a potential biomarker for its monitoring." (PMID 40507962, 2025). "RUNX2 overexpression in malignancies such as osteosarcoma contributes to increased VEGF production and enhances anti-apoptotic signalling within hypoxic microenvironments." (PMID 40806771, 2025). "Runt-related transcription factor-2 (RUNX2) is an integral player in osteogenesis and is highly expressed in osteosarcoma." (PMID 40806771, 2025). "RUNX2 plays a crucial role in osteosarcoma by stimulating angiogenesis, promoting metastasis and proliferation, enhancing cancer stemness, and contributing to drug resistance." (PMID 40806771, 2025). "RUNX2 is the only gene significantly overexpressed in osteosarcoma with a poor chemotherapy response." (PMID 40806771, 2025).
osteosarcoma (continued). "Another study revealed that circ_0076684 and RUNX family transcription factor 2 (RUNX2) mRNA are significantly upregulated in osteosarcoma cells due to transcriptional activation mediated by Chromobox homolog 4 (CBX4)." (PMID 40161373, 2025). "Together, RUNX2 and HIF-1α collaboratively enhance the metastatic and invasive potential of osteosarcoma, where RUNX2 upregulates MMPs and other enzymes to degrade the extracellular matrix and HIF-1α supports this process through EMT." (PMID 40806771, 2025). "RUNX2 is often upregulated in cancers, such as osteosarcoma, colon cancer, prostate cancer, thyroid cancer, and melanoma, underscoring its oncogenic role." (PMID 40806771, 2025). "For example, in an osteosarcoma cell line study, RUNX2 silencing inhibited invasion capacity by suppressing VEGF, MMP-2, and MMP-9 expression." (PMID 40806771, 2025). "For example, in mouse and human osteosarcoma cell lines, RUNX2 knockdown increased the release of extrinsic ligand FAs, adaptor protein FADD, and intrinsic apoptotic marker cytochrome C." (PMID 40806771, 2025). "Numerous studies have demonstrated that miRNAs are aberrantly expressed in osteosarcoma and play direct or indirect roles in controlling the expression of RUNX2." (PMID 40806771, 2025). "Patients with advanced stages of osteosarcoma overexpressing RUNX2 are more likely to have high tumour grades, metastasis, and lower overall or progression-free survival rates." (PMID 40806771, 2025). "To functionally validate this phenotype, we engineered RUNX2-overexpressing osteosarcoma cells that exhibited increased osteogenic differentiation." (PMID 40410897, 2025). "We demonstrated that the knockdown of ITGB3 increased radiosensitization by promoting osteogenic differentiation and apoptosis through activation of the JNK/c-JUN/RUNX2 pathway in osteosarcoma." (PMID 40410897, 2025). "In the context of bone tumor research, the interaction between WWOX and RUNX2 has been extensively studied in osteosarcoma." (PMID 41141138, 2025). "Osteosarcoma and chondrosarcoma cells express Runx2 and Sox9 genes, indicating osteogenic and chondrogenic differentiation, respectively." (PMID 39896817, 2024). "Further, BRD4 enrichment was observed on the RUNX2 gene, which drives essential genes from drug resistance in osteosarcoma cells." (PMID 38172984, 2024). "Osteosarcoma cells express Runx2 and Sox9 genes, showing features of osteoblastic and chondrogenic differentiation." (PMID 39896817, 2024). "Heat shock protein 90 (HSP90) can reduce the expression of Runx2 by inhibiting the action of β‐catenin, thereby promoting apoptosis and inhibiting proliferation in osteosarcoma cells." (PMID 38800967, 2024). "Mechanistically, GCN5 is recruited to sustain H3K27ac in the Runx2 promoter to transcriptionally upregulate Runx2, consequently facilitating lung metastasis in osteosarcoma." (PMID 38374872, 2024). "CBX4 can recruit GCN5 to the RUNX2 promoter, leading to upregulated RUNX2 expression in osteosarcoma." (PMID 38816356, 2024). "An analysis of osteosarcoma-related gene expression indicates that overexpression of RUNX2 can be a potential biomarker for chemotherapy failure in patients with osteosarcoma." (PMID 38430423, 2024). "At the molecular level, CBX4 recruits GCN5 to the Runx2 promoter, upregulating Runx2 at the transcriptional level, thereby promoting osteosarcoma cell migration and invasion." (PMID 39062505, 2024). "The objective for the generation of these RNA-Seq and metabolome datasets was to identify the effects of RUNX2 silencing on the gene expression pattern and metabolite profile in osteosarcoma cells and provide raw data." (PMID 37663774, 2023). "Studies of osteosarcoma tumors have revealed that levels of RUNX2 DNA, RNA, and protein are significantly elevated in osteosarcoma tumors." (PMID 37197432, 2023). "RUNX2 knockdown in SAOS2 reduced SOX9 mRNA and protein levels, and the regulation of SOX9 by RUNX2 is conserved in mouse osteosarcoma cells." (PMID 37491298, 2023).
osteosarcoma (continued). "Anomalously heightened levels of RUNX2—spanning its DNA, RNA, and protein manifestations—have been discernibly charted in osteosarcoma tumors." (PMID 38140058, 2023). "In the near future, we will continue to explore the mechanism of circ_001722/miR-204-5p/RUNX2 axis in Osteosarcoma chemotherapy resistance and patient prognosis, and try to find targets for treatment of osteosarcoma and resistance to drug resistance." (PMID 37453970, 2023). "A similar function of RUNX2 was reported elsewhere: overexpression of RUNX2 in U2OS osteosarcoma cells reversed the effect mediated by miRNA-218, a direct interactive target of Runx2, and promoted cancer cell migration and invasion." (PMID 37108164, 2023). "In another osteosarcoma study, amplification of RUNX2 was found in both the primary tumor and the metastatic tumor." (PMID 37108164, 2023). "Due to RUNX2’s complex activity in growing osteoblasts, it is possible that its dysregulation contributes to osteosarcoma pathogenesis." (PMID 37370857, 2023). "We analysed the expression levels of FBXW11 in normal osteoblasts and osteosarcoma cells expressing higher RUNX2 levels." (PMID 37199076, 2023). "•The transcriptome dataset can be used by researchers to identify novel targets of RUNX2 and elucidate the molecular mechanism of RUNX2 in osteosarcoma tumorigenesis." (PMID 37663774, 2023). "RUNX2 is involved in the long noncoding RNA HLA complex group 18 (LncRNA HCG18)-elicited tumorigenic phenotype in osteosarcoma." (PMID 37108164, 2023). "RUNX2 also inhibited the proliferation of osteogenic potential cells and osteosarcoma cells, and transfection of siRNA against RUNX2 into human mesenchymal stem cells increased their proliferation." (PMID 38003654, 2023). "RUNX2 was significantly decreased by transfection of a miRNA-218 mimic, and RUNX2 expression was obviously increased by treatment with a miRNA-218 inhibitor in osteosarcoma U2OS cells." (PMID 37108164, 2023). "The oncogenic functions of RUNX2 were first identified in regulation of osteogenesis and strongly related to the progression of osteosarcoma." (PMID 37519798, 2023). "Over the last several years, many investigations on osteosarcoma samples have shown abnormally high levels of RUNX2 protein." (PMID 37370857, 2023). "The increase and amplification of RUNX2 due to chromosome 6p12-p21 instability has been shown by several investigations, including biopsies, to be an early event in the etiology of osteosarcoma." (PMID 37370857, 2023). "RUNX2 is involved in a wide variety of cancers, including gastric cancer, breast renal cell carcinoma, and osteosarcoma." (PMID 37370857, 2023). "In a study of osteosarcoma, RUNX2 was knocked down in MG63 and U2OS cells, which sensitized osteosarcoma cells to the chemotherapy treatment of cisplatin." (PMID 37108164, 2023). "Comparing 22 osteosarcomas, we found that the average mRNA overexpression of RUNX2 was 3.3-fold greater in tumors that had a poor response to neoadjuvant chemotherapy (90% necrosis) than in tumors that had a favorable response (>90% necrosis)." (PMID 37370857, 2023). "•The metabolome dataset can be used by researchers to elucidate the role of RUNX2 in metabolic reprogramming in osteosarcoma." (PMID 37663774, 2023).